DSC1 (desmocollin 1)
Description:
A component of desmosome cell-cell junctions which are required for positive regulation of cellular adhesion (By similarity). Required for desmosome adhesion strength between the granular layers of the epidermis, as a result moderates epidermal proliferation and differentiation (By similarity). Is therefore required to maintain postnatal epidermal barrier function and normal hair follicle morphology into adulthood (By similarity).
Synonyms: DG2/DG3; CDHF1
Tractability: Antibody: UniProt places it where antibodies can reach, with high confidence; its Gene Ontology location is reachable by antibodies, with high confidence; UniProt predicts a signal peptide or a membrane-spanning region.
Gene: Protein-coding gene on chromosome 18 (31,129,236 to 31,162,856, reverse strand). Ensembl gene ENSG00000134765.
Subcellular location: Cell membrane; Cell junction, desmosome
Pathways (Reactome):
Developmental Biology: Formation of the cornified envelope; Keratinization
Immune System: Neutrophil degranulation
Gene Ontology:
Molecular function: protein binding; calcium ion binding
Biological process: cell-cell adhesion; desmosome maintenance; establishment of skin barrier; hair follicle morphogenesis; negative regulation of epithelial cell proliferation; cell adhesion; homophilic cell-cell adhesion
Cellular component: extracellular exosome; plasma membrane; cornified envelope; desmosome; ficolin-1-rich granule membrane; gap junction; membrane; cell junction
Genetic constraint (gnomAD): Loss-of-function variants: 79 observed, 100.19 expected, observed/expected ratio (o/e) 0.79, 90% interval 0.66 to 0.95. The upper end of that interval is the gene's LOEUF score, 0.95, which puts it in group 4 of 6, group 1 being the genes least tolerant of losing a copy. Missense variants: 1,107 observed, 1,115.3 expected, observed/expected ratio (o/e) 0.99, 90% interval 0.94 to 1.04. Synonymous variants: 405 observed, 387.45 expected, observed/expected ratio (o/e) 1.05, 90% interval 0.96 to 1.13.
Homologues: Orthologues: chimpanzee DSC1 (99% identical), macaque DSC1 (95% identical), rabbit DSC1 (85% identical), pig DSC1 (84% identical), rat Dsc1 (82% identical), mouse Dsc1 (82% identical), guinea pig DSC1 (70% identical), tropical clawed frog dsc3 (37% identical), zebrafish dsc2l (35% identical). Paralogues in human: DSC2 (55% identical), DSC3 (51% identical), DSG4 (28% identical), DSG2 (26% identical), DSG3 (26% identical), DSG1 (22% identical).
Diseases named in the same sentence as DSC1 in open-access papers:
DSC1 is named in the same sentence as 49 diseases in open-access papers, as found by Europe PMC text mining. Sharing a sentence is not in itself a finding about the gene and the disease. The quoted sentences say what the papers report.
colorectal cancer (6 papers, 2006 to 2025). A primary or metastatic malignant neoplasm that affects the colon or rectum. "In human medicine, decreased expression of DSC1 was related to the poor differentiation and prognosis of head and neck squamous cell carcinoma, lung cancer, melanoma, and colorectal carcinoma." (PMID 37760246, 2023). "Low expression of desmocollins including DSC1 in colorectal carcinoma was related to higher tumor grade." (PMID 37620794, 2023). "In this report, we show for the first time that Dsc2 protein expression is reduced in colorectal cancer, and that this is accompanied by de novo expression of Dsc1 and Dsc3." (PMID 17088906, 2006).
IgA pemphigus (5 papers, 2014 to 2025). Immunoglobulin A (IgA) pemphigus is a group of newly characterized immune-mediated intraepidermal blistering skin diseases. "In the SPD variant of IgA pemphigus, human desmocollin 1 is the autoantigen targeted by IgA autoantibodies." (PMID 34684041, 2021). "Autoantibodies to desmosomal proteins, DSG1 and DSC1 proteins are a hallmark of blistering skin conditions including pemphigus foliaceus and IgA pemphigus." (PMID 24497829, 2014). "The target antigen in the SPD type of IgA pemphigus is desmocollin 1, another desmosomal cadherin protein." (PMID 34684117, 2021). "In SPD-type IgA pemphigus, IgA autoantibodies primarily target desmocollin 1 (Dsc1), while the antigen in IEN remains unclear." (PMID 40372624, 2025).
pemphigus (5 papers, 2021 to 2023). Pemphigus is a group of rare autoimmune diseases that cause blistering of the skin and mucous membranes (mouth, nose, throat, eyes, and genitals).This conditioncan occur at any age, but often strikes people in middle or older age. "Then, we established more sensitive ELISAs using Dsc1‐3 RPs produced in mammalian expression system that detect IgG anti‐Dsc autoantibodies frequently in atypical variants of pemphigus such as PNP, PH, and PVeg, but rarely in classical pemphigus." (PMID 36578135, 2023). "Previous studies have shown that IgG and IgA antibodies in patients with IgG/IgA pemphigus could target Dsg1, Dsg3, and/or desmocollin 1 (Dsc1)–Dsc3 to a different extent, which may account for the mixed clinical presentations of the disease." (PMID 35625932, 2022). "Mice lacking Dsc1 (Dsc1−/−) showed epidermal fragility resembling pemphigus, and defects of epidermal barrier function." (PMID 36578135, 2023).
breast carcinoma (4 papers, 2022 to 2026). "We show association of DSC1, protein previously linked with lymph node metastasis of luminal A breast tumors, with increased metastatic potential of luminal A breast cancer cells in vitro." (PMID 37620794, 2023). "Our data indicate that DSC1 is connected to cell migration, invasion, and cell cycle regulation in luminal A breast cancer cells, and can be effectively modulated by parthenolide." (PMID 37620794, 2023). "Increased levels of DSC1 were also observed in higher grade and HER2 + breast cancer subtypes and was associated with worse distant metastasis free survival in lymph node positive breast tumors." (PMID 37620794, 2023). "In the present study we tested these inhibitors to identify a modulator of DSC1 expression in luminal A breast cancer cells." (PMID 37620794, 2023). "Enrichment of this pathway supports the findings of association between DSC1 and proteins involved in proliferation in MCF7 breast cancer cells with potential to promote breast tumor aggressiveness and metastatic behavior." (PMID 37620794, 2023). "Our systems biology data indicate that DSC1 is connected to mechanisms of cell cycle regulation in luminal A breast cancer cells, and can be effectively modulated by parthenolide." (PMID 37620794, 2023). "In our previous study, we identified desmocollin-1 (DSC1) as a protein more abundant in more migrating population of MDA-MB-231 breast cancer cell line." (PMID 37620794, 2023). "In the context of breast cancer, our previous study revealed increased protein levels of DSC1 in luminal A breast tumors that invaded regional lymph nodes compared to lymph node negative luminal A breast tumors." (PMID 37620794, 2023). "According to other studies, the DSC1 is validated as a protein connected with the lymph node status of breast cancer luminal A patients and positive for Her-2 status, as demonstrated by immunohistochemistry in primary breast tumors." (PMID 36293530, 2022). "Moreover, our results indicate potential regulation of DSC1 by NF-κB inhibitor parthenolide as we identified parthenolide to reduce DSC1 protein levels in MCF7 breast cancer cells as well as expression of IGFBP5, LACRT genes and proliferative pathway." (PMID 37620794, 2023). "From these results we suggest that parthenolide treatment could target cellular mechanisms connected to DSC1 in luminal A breast cancer cells." (PMID 37620794, 2023). "Therefore, we focused on DSC1 role in cellular and molecular mechanisms in luminal A breast cancer and its possible therapeutic modulation." (PMID 37620794, 2023). "Herein, we firstly investigated DSC1 modulation in breast cancer." (PMID 37620794, 2023). "Based on these findings we hypothesize that DSC1 may play a role in metastasis of luminal A breast cancer and has a potential to serve as a therapeutic target." (PMID 37620794, 2023). "Here we aim at understanding the molecular role of DSC1 in breast cancer cells using proteomics and RNA sequencing (RNA-Seq), analysis of its role in cell morphology, and at proposing the inhibitor that can modulate DSC1 protein levels and DSC1-related molecular mechanisms." (PMID 37620794, 2023). "Moreover, we confirmed DSC1 to increase migration and invasion of MCF7 breast cancer cell line in vitro." (PMID 37620794, 2023).
melanoma (4 papers, 2016 to 2023). A malignant, usually aggressive tumor composed of atypical, neoplastic melanocytes. "DSC1 was also overexpressed in primary melanoma and downregulated in melanoma metastases." (PMID 37620794, 2023). "In contrast, expression of other desmosomal cadherins (DSG1, DSG3, DSC1, DSC2, DSC3) was negligible, revealing that DSG2 is unique within this gene family for its expression in a large proportion of melanoma cell lines." (PMID 27340778, 2016).
lung carcinoma (3 papers, 2018 to 2023). "Decreased desmocollin 1 (DSC1) expression is associated with poor prognosis in human lung cancer." (PMID 29855376, 2018).
atherosclerosis (2 papers, 2023 to 2025). A disease characterized by the build-up of fatty material and calcium deposition in the arterial wall resulting in partial or complete occlusion of the arterial lumen. "The successful targeting of DSC1 with DTX has not only provided the opportunity to repurpose the chemotherapy drug DTX for use in reducing atherosclerosis, but has also opened the door to targeting DSC1-apoA-I interactions with other therapeutic agents, such as peptides and monoclonal antibodies." (PMID 36831097, 2023).
Autoimmunity (2 papers, 2019 to 2023). The occurrence of an immune reaction against the organism's own cells or tissues. "Previous studies had shown that DSC1 functions in part through its association with the Calmodulin Binding Transcription Activator 3 (CAMTA3), which acts as a negative regulator of immunity to inhibit DCS1‐induced autoimmunity." (PMID 30957942, 2019). "Furthermore, the autoimmunity exhibited by lines expressing CG-1 domain mutants could also be due to the monitoring of the transcriptional activity of CAMTA3 either by DSC1/DSC2 or other NLRs, or the CAMTA3-NLRs complex may modulate the CAMTA3 transcriptional activity." (PMID 37566065, 2023).
bladder tumor (2 papers, 2023 to 2025). "From the identified signature gene set, MDGA2, GNLY, DLX1, and DSC1 were selected for expression analysis in bladder tumors and matching blood samples of 10 BLCA patients." (PMID 37876438, 2023). "While DSC1 had a statistically significant difference in the bladder tumor to blood ratio, DLX1 had the opposite effect on the bladder tumor to blood ratio." (PMID 37876438, 2023).
breast tumor (2 papers, 2022 to 2023). "DSC1 was previously associated with lymph node metastasis of luminal A breast tumors and was found to increase migration and invasion of MCF7 cells in vitro." (PMID 37620794, 2023). "Subsequently, immunohistochemical analysis of 96 primary breast tumors revealed increased levels of DSC1 in lymph node positive luminal A tumors compared to their lymph node negative counterparts." (PMID 37620794, 2023). "Based on this evidence we suggested that DSC1 could be involved in metastatic mechanisms of luminal A breast tumors." (PMID 37620794, 2023). "Based on these results we conclude that DSC1 could be involved in breast tumor proliferation and development in the early stage, and in tumor cell adhesion to metastatic sites in the later stage of the disease supporting generation of secondary tumors." (PMID 37620794, 2023).
ovarian carcinoma (2 papers, 2021 to 2024). A malignant neoplasm originating from the surface ovarian epithelium. "For instance, CircRAB11FIP1 promotes ovarian cancer via miR‐129/DSC1 axis (Zhang, Zhu, & Hu, 2021), circEPSTI1 upregulates SLC7A11 expression in cervical cancer by miR‐375 and circ_0110389 accelerates gastric cancer through miR‐127‐5p/SORT1." (PMID 39632246, 2024).
subcorneal pustular dermatosis (2 papers, 2021 to 2023). A rare, benign, chronic disease characterized by sterile pustular eruption, typically involving the flexural sites of the trunk and proximal extremities. "In addition to the presence of four desmosomal Dsg isoforms, i.e. Dsg1‐4, Dsc1, 2 and 3, all of which are derived from different genes, Dsc1 has been previously identified as the target antigen of IgA autoantibodies in the subcorneal pustular dermatosis (SPD)‐type of intercellular IgA dermatosis." (PMID 36578135, 2023).
alopecia (1 paper, 2017). Hair loss usually from the scalp. "Although Dsc1 deficient mice show normal HF cycling and structures until the age of four weeks, they develop alopecia and HF degeneration in later life." (PMID 28228108, 2017).
anal carcinoma (1 paper, 2012). "We have studied the expression of the desmosomal proteins DSG1 and DSC1 in anal carcinoma and their relation to survival." (PMID 22333708, 2012). "Protein expression of desmoglein-1 (DSG1), desmocollin-1 (DSC1) and E-cadherin was studied by immunohistochemistry in a cohort of 53 anal carcinoma patients treated by radiation alone or combined with 5-fluorouracil and mitomycin C." (PMID 22333708, 2012). "Multivariate survival analyses identified DSG1 and DSC1-status to be an independent prognostic variable for CSS in this cohort of anal carcinoma patients when expression of these two proteins was categorised as one variable." (PMID 22333708, 2012). "In a cohort of 53 anal cancer patients, DSG1, DSC1 and additionally E-cadherin were analysed at the protein level by IHC." (PMID 22333708, 2012).
asthma (1 paper, 2023). "Univariable linear regression analyses for DSG1, DSC1 and JUP identified that a history of BPD had significant association with each of these three proteins (β−0.23, p = 0.014; β−0.27, p = 0.019; β−0.23, p = 0.008 respectively) but sex, age, diagnosis of asthma and low lung function did not." (PMID 37147394, 2023).
atopic dermatitis (1 paper, 2024). "Furthermore, in atopic dermatitis, corneodesmosomal proteins such as desmoglein 1 and desmocollin 1 exhibited elevated levels compared with normal or non-lesional skin, indicating increased cell-to-cell adhesion, which may have a relation to the regulation of H2 expression in atopic dermatitis skin." (PMID 39420441, 2024).
colitis (1 paper, 2006). Inflammation of the colon. "Loss of Dsc2 (8/19) and de novo expression of Dsc1 (11/19) and Dsc3 (6/19) was also found in colorectal adenocarcinomas on a background of colitis." (PMID 17088906, 2006). "In tumours on a background of colitis, loss of Dsc2 was observed in eight of 19 specimens examined, and de novo expression of Dsc1 and Dsc3 was detected in 11 of 19 and six of 19 specimens respectively." (PMID 17088906, 2006).
colon cancer (1 paper, 2024). "Regarding expression in colon cancer cell lines, KM12SM and HCT116 exhibited high levels of DSC1, while CDH17 was more abundant in the epithelial cell lines KM12SM and HT-29." (PMID 38263178, 2024).
colorectal adenocarcinoma (1 paper, 2006). The most common type of colorectal carcinoma. "We have found switching between desmocollins in sporadic colorectal adenocarcinoma with a reduction in Dsc2 protein (in 8/16 samples analysed by immunohistochemistry) being accompanied by de novo expression of Dsc1 (16/16) and Dsc3 (7/16)." (PMID 17088906, 2006).
colorectal tumors (1 paper, 2023). "For instance, DSC1 was found overexpressed in liver metastasis of colorectal tumors and a lack of DSC1 protein in squamous cell carcinoma was associated with increased patient survival." (PMID 37620794, 2023).
Fulminant hepatitis (1 paper, 2021). Acute hepatitis complicated by acute liver failure with hepatic encephalopathy occurring less than 8 weeks after the onset of jaundice. "Taken together, these results suggest that Fuc-S-α-CDE (G2, DSC1, DSF2) has the potential for a novel Kupffer cell-selective NF-κB decoy carrier for the treatment of LPS-induced fulminant hepatitis in mice." (PMID 34064866, 2021). "Intravenous injection of Fuc-S-α-CDE (G2, DSC1, DSF2)/NF-κB decoy complex extended the survival of LPS-induced fulminant hepatitis model mice." (PMID 34064866, 2021). "Moreover, the serum aspartate aminotransferase (AST), alanine aminotransferase (ALT), and TNF-α levels in LPS-induced fulminant hepatitis model mice were significantly attenuated by the treatment with Fuc-S-α-CDE (G2, DSC1, DSF2)/NF-κB decoy complex, compared with naked NF-κB decoy alone." (PMID 34064866, 2021).
glioblastoma (1 paper, 2021). The most malignant astrocytic tumor (WHO grade IV).
gout (1 paper, 2022). A condition characterized by painful swelling of the joints, which is caused by deposition of urate crystals. "As for the bioinformatic analysis of the highly expressed proteins in every group, the highly expressed proteins in gout including alpha-1-acid glycoprotein 1, desmocollin-1, and hornerin were significantly involved in “neutrophil degranulation”." (PMID 35359923, 2022).
Hyperkeratosis (1 paper, 2021). Hyperkeratosis is a histopathological term defining a thickened stratum corneum and may be present in many different skin conditions, with many possible overlaps. "Then, KLK5 and KLK7 induced proteolysis of desmocollin 1 (DSC-1), one of corneodesmosonal components, which is involved in hyperkeratosis." (PMID 33652999, 2021).
keloid (1 paper, 2022). An irregularly shaped, elevated mark on the skin caused by deposits of excessive amounts of collagen during wound healing. "Moreover, several proteins that play a role in cell junctions were also downregulated in keloids, including EVPL, PPL, DSP, PKP1, PKP3, DSC1, DSG1, and FLG." (PMID 35435317, 2022).
lymph node metastases (1 paper, 2012). "Statistically significant predictors of reduced CSS survival were radiation without chemotherapy, large tumour size and lymph node metastases and positive staining for both DSG1 and DSC1." (PMID 22333708, 2012).
malaria (1 paper, 2013). Malaria is a serious and sometimes fatal disease caused by a parasite that commonly infects a certain type of mosquito which feeds on humans. "Interestingly, the DSC1 knockout flies were also more susceptible to pyrethroid insecticides, which are used globally as a major weapon against the malaria-carrying mosquitoes." (PMID 23505382, 2013). "In addition, because the DSC1 mutants are more susceptible to pyrethroids, DSC1 channel blockers may be useful to enhance the efficacy of pyrethroids, which are currently a key weapon against numerous agriculturally and medically important arthropod pests, including malaria-transmitting mosquitoes." (PMID 23505382, 2013).
nematode infection (1 paper, 2020). "To study whether DSC1 and WRKY19 were involved in susceptibility of Arabidopsis to M. incognita, we also tested the homozygous Arabidopsis T-DNA insertion lines dsc1–1 and wrky in nematode infection assays." (PMID 32054439, 2020). "We therefore investigated if the expression of DSC1 and WRKY19 is indeed regulated during root development and nematode infections in wildtype Arabidopsis plants using quantitative reverse transcription PCR (qRT-PCR) with gene specific primers." (PMID 32054439, 2020). "The lack of change in DSC1 gene expression seems inconsistent with the observed increase in nematode infection on the dsc1–1 mutant plants." (PMID 32054439, 2020).